CCDC92 (coiled-coil domain containing 92)
Description:
Interferon-stimulated protein that plays a role in innate immunity. Strongly inhibits ebolavirus transcription and replication. Forms a complex with viral RNA-bound nucleocapsid NP and thereby prevents the transport of NP to the cell surface.
Synonyms: FLJ22471
Tractability: PROTAC: ubiquitination databases record sites on it; its protein half-life has been measured.
Gene: Protein-coding gene on chromosome 12 (123,918,660 to 123,974,253, reverse strand). Ensembl gene ENSG00000119242.
Subcellular location: Cytoplasm, cytoskeleton, microtubule organizing center, centrosome, centriole; Cytoplasm
Subcellular location (Human Protein Atlas): Centrosome; Nucleoplasm; Vesicles
Gene Ontology:
Molecular function: identical protein binding; protein binding
Cellular component: centriole; centrosome; cytoplasm
Genetic constraint (gnomAD): Loss-of-function variants: 9 observed, 21.28 expected, observed/expected ratio (o/e) 0.42, 90% interval 0.25 to 0.74. The upper end of that interval is the gene's LOEUF score, 0.74, which puts it in group 3 of 6, group 1 being the genes least tolerant of losing a copy. Missense variants: 376 observed, 420.8 expected, observed/expected ratio (o/e) 0.89, 90% interval 0.82 to 0.97. Synonymous variants: 180 observed, 187.44 expected, observed/expected ratio (o/e) 0.96, 90% interval 0.85 to 1.09.
Homologues: Orthologues: chimpanzee CCDC92 (99% identical), macaque CCDC92 (96% identical), pig CCDC92 (89% identical), rabbit CCDC92 (85% identical), mouse Ccdc92 (82% identical), dog CCDC92 (81% identical), guinea pig CCDC92 (79% identical), tropical clawed frog ccdc92 (74% identical), rat Ccdc92 (73% identical), zebrafish ccdc92 (66% identical). Paralogues in human: CCDC92B (26% identical).
Diseases named in the same sentence as CCDC92 in open-access papers:
CCDC92 is named in the same sentence as 15 diseases in open-access papers, as found by Europe PMC text mining. Sharing a sentence is not in itself a finding about the gene and the disease. The quoted sentences say what the papers report.
Insulin resistance (5 papers, 2018 to 2025). Increased resistance towards insulin, that is, diminished effectiveness of insulin in reducing blood glucose levels. "Given that the CCDC92 (coiled-coil domain containing 92) was important in insulin resistance, we sought to investigate whether the CCDC92 rs825476 SNP is associated with the risk of CHD in Chinese Han population." (PMID 29439709, 2018). "Recent phenotypic analysis of Ccdc92 knockout (KO) mice has demonstrated that CCDC92 is involved in obesity and insulin resistance by mediating the inflammatory response in white adipose tissue." (PMID 41378450, 2025). "The top-ranked gene at this locus, CCDC92, has been shown to play a role in insulin resistance and subcutaneous adipose and peripheral fat28." (PMID 39653778, 2024). "Given that the CCDC92 was important in insulin resistance, we sought to investigate whether CCDC92 plays role in the development of CHD." (PMID 29439709, 2018).
Obesity (3 papers, 2024 to 2025). Accumulation of substantial excess body fat. "A recent study using a different Ccdc92 KO mouse model showed that the KO mice developed reduced obesity and increased insulin sensitivity under high-fat diet conditions, indicative of a function of CCDC92 in the white adipose tissue." (PMID 41378450, 2025).
atherosclerosis (1 paper, 2023). A disease characterized by the build-up of fatty material and calcium deposition in the arterial wall resulting in partial or complete occlusion of the arterial lumen. "We used the endothelial marker gene CDH5 to identify a cluster of endothelial cells and confirmed that these cells express DHX38, MAT2A, CCDC92, FES and FURIN, prompting future efforts to dissect the role of these genes in this cell type in atherosclerosis." (PMID 36928188, 2023).
diabetes (1 paper, 2022). "Several diabetes risk variants increased the expression of genes in multiple tissues, including AP3S2 (rs4932265-T), CCDC92 (rs7978610-G), HLA-DQA2 (rs601945-G) and a lncRNA RP11-252K23.2 (rs3115960-G)." (PMID 35568807, 2022).
diabetic kidney disease (1 paper, 2025). Progressive kidney disorder caused by vascular damage to the glomerular capillaries, in patients with diabetes mellitus. "CCDC92 promotes podocyte lipotoxicity by dysregulating lipid homeostasis via ABCA1 signaling, leading to lipid accumulation and podocyte damage in diabetic kidney disease." (PMID 41009556, 2025).
Ebola (1 paper, 2020). "A comprehensive study of one ISG (CCDC92) that shows anti-Ebola activity in our screen reveals that CCDC92 can inhibit viral transcription and the formation of complete virions via an interaction with the viral protein NP." (PMID 32528005, 2020).
male infertility (1 paper, 2025). The inability of the male to effect fertilization of an ovum after a specified period of unprotected intercourse. "In this study, we find that CCDC92 deficiency in mice leads to severe abnormalities of the sperm head and flagellum and causes male infertility." (PMID 41378450, 2025). "To dissect the molecular mechanism underlying CCDC92-associated male infertility, we performed co-immunoprecipitation (coIP) coupled with mass spectrometry to identify interacting partners of CCDC92." (PMID 41378450, 2025). "Overall, our investigations elucidate Ccdc92 as a causative gene of male infertility in mice and establish functional links between CCDC92, IFT, and axonemal MIPs during spermiogenesis." (PMID 41378450, 2025). "Our findings demonstrate an essential role of CCDC92 in regulating spermatid shaping and provide novel insights into the pathology of male infertility." (PMID 41378450, 2025). "In this study, we show that Ccdc92 KO results in male infertility in mice." (PMID 41378450, 2025). "Despite no apparent morphological alterations in Ccdc92 KO mice, CCDC92 deficiency leads to malformed sperm heads and defective flagella in mature spermatozoa, resulting in male infertility." (PMID 41378450, 2025).
teratozoospermia (1 paper, 2025). "CASA also revealed that a significant proportion of the Ccdc92 KO spermatozoa displayed abnormal morphology, indicative of teratozoospermia in Ccdc92 KO males." (PMID 41378450, 2025).
type 2 diabetes (1 paper, 2023). "In a bivariate GWAS, a novel signal at rs825476 near CCDC92, which is also an expression quantitative trait locus (eQTL) for this gene, was identified as a shared locus between type 2 diabetes and CHD." (PMID 37540242, 2023). "Ten VAT-specific candidate genes were associated with type 2 diabetes after Bonferroni correction, including five causal genes supported by SMR and co-localisation: PABPC4 (1p34.3); CCNE2 (8q22.1); HAUS6 (9p22.1); CWF19L1 (10q24.31); and CCDC92 (12q24.31)." (PMID 37540242, 2023). "Besides, genetically elevated expression of CCNE2 on 8q22.1, HAUS6 on 9p22.1, CWF19L1 on 10q24.31, CCDC92 on 12q24.31 and DNAH10OS on 12q24.31 showed protective effects on type 2 diabetes risk." (PMID 37540242, 2023).
virus infection (1 paper, 2020). "In HEK-293T VP30 cells expressing wild-type CCDC92 or the deletion mutant that still interacted with NP (CCDC92 ∆20–72), we still observed inhibition of virus infection as indicated by a reduction in virus-driven luciferase expression." (PMID 32528005, 2020).
cancer (1 paper, 2022). A tumor composed of atypical neoplastic, often pleomorphic cells that invade other tissues. "CCDC92 was dramatically deregulated in pan-cancer patients with a worse prognosis, with a fold change ≥ 1.2." (PMID 35813478, 2022).
infection (1 paper, 2020). The state of being infected such as from the introduction of a foreign agent such as serum, vaccine, antigenic substance or organism. "This may suggest that CCDC92 has a role in cell susceptibility to EBOV or tissue tropism during infection." (PMID 32528005, 2020). "The three ISGs with the most significant inhibitory effect, PFKFB3, BTN3A3, and CCDC92, decreased EBOV∆VP30 titers by nearly 1000-fold on day 6 post infection." (PMID 32528005, 2020). "Western blot analysis confirmed the expression of each CCDC92 construct and VP30 before infection." (PMID 32528005, 2020).
CCDC92 also shares sentences with these, for which no sentence is quoted: cardiac disease (1 paper); coronary artery diseases (1); osteosarcoma (1).